SMAD2 (SMAD family member 2)
Diseases named in the same sentence as SMAD2 in open-access papers (continued):
Sharing a sentence is not in itself a finding about the gene and the disease.
gastric cancer (continued). "The expression level of SMAD2 was not correlated with OS of mixed gastric cancer patients (HR = 2.54(0.57–11.34), P = 0.2." (PMID 34138687, 2021). "MiR-204 inhibits the phosphorylation of SMAD2 and SMAD3 by directly targeting TGF-β receptor 2, which further contributes to the inhibition of EMT and elevates the sensitivity to 5-fluorouracil in gastric cancer cells." (PMID 34686196, 2021). "In addition, EMT regulators, such as Snail and Slug, were upregulated in lysates and exosomes derived from DSGOST-treated gastric cancer cells, and TGFβ1 plus DSGOST treatment induced EMT signaling via phosphorylation of Smad2 and Smad3." (PMID 29844404, 2018). "Exposure of LNT-229 or LN-308 cells to recombinant GDF-15 did not trigger Smad2 or Smad1/5/8 phosphorylation, a finding that is in line with previous reports in gastric cancer cells." (PMID 26741507, 2016). "Contrary to colorectal and hepatocellular carcinoma, canonical carboxy-terminal phosphorylation, but not linker phosphorylation, of Smad2 is critical for gastric cancer." (PMID 22539990, 2012). "Real time PCR demonstrated reduced mRNA expression of Smad2 in gastric cancer when compared with surrounding non-tumor tissue in 15/16 patients." (PMID 22539990, 2012). "The overexpression of phospho-Smad2 was observed in scirrhous gastric cancer cells, but not in non-scirrhous gastric cancer cells." (PMID 20145621, 2010). "TβR-I, TβR-II, and phospho-Smad2 expressions were found in scirrhous gastric cancer cells, but not in non-scirrhous gastric cancer cells." (PMID 20145621, 2010). "Not much is known regarding the prognostic value of Smad2 expression in gastric carcinoma, while several reports of serum levels of TGFβ suggested that TGFβ can induce invasion and metastasis in gastric carcinoma." (PMID 21110833, 2010). "Although Smad signal is a critical integrator of TGFβ receptor signaling transduction systems, not much is known about the role of Smad2 expression in gastric carcinoma." (PMID 21110833, 2010). "However, its downregulation led to the promotion of proliferation, colony formation, EMT, and migration of gastric cancer cells (BGC-823 and SGC-7901), along with increased TGF-β signaling pathway-related proteins, including TGF-β, phospho-Smad2, Smad2, Smad3, and Smad4." (PMID 39768197, 2024). "In our cluster analysis of the TCGA data of gastric cancer patients with N2 and N3 metastasis, the cases with high ERBB2 expression formed clusters with cases that showed high SMAD2 expression, but not with the cases with a high expression of TGFB1, which is an upstream cytokine of SMAD2 signaling." (PMID 35650563, 2022). "In gastric cancer (GC), evidence presents that MSCs secreted TGF-β1 promotes fatty acid oxidation (FAO) to support stemness features and drug resistance, which is mediated by activating SMAD2 and SMAD3 and promoting lncRNA MACC1AS1 expression." (PMID 34095111, 2021). "Furthermore, TGF-β stimulated the phosphorylation of Smad2 in scirrhous gastric cancer cells as previously reported, but not in non-scirrhous gastric cancer cells, suggesting that TGF-β signalling is active in scirrhous gastric cancer, but not in non-scirrhous gastric cancer." (PMID 20145621, 2010).
colorectal cancer (81 papers, 1998 to 2026). A primary or metastatic malignant neoplasm that affects the colon or rectum. "Although periostin and Smad2/3 signaling have been independently linked to cancer progression, their expression patterns and correlations remain insufficiently understood in colorectal cancer (CRC)." (PMID 39941916, 2025). "Our results demonstrate that periostin is strongly expressed in cancer-associated fibroblasts (CAFs) and is closely associated with Smad2/3 expression, as well as malignant clinicopathological characteristics in colorectal cancer." (PMID 39941916, 2025). "To elucidate the mechanisms of cancer development and dynamics of the linker threonine-phosphorylated Smad2/3 (pSmad2/3L-Thr)-positive cells, we explored the early stages of colitis-associated colorectal cancer in AOM/DSS mice." (PMID 37511456, 2023). "Despite some reports pointing to an absence of acquired mutations, insertions, or microdeletions in Smad3 in the skin and parathyroid tumors, its somatic mutation associated with Smad2 and Smad4 mutations is a cause of sporadic colorectal carcinoma." (PMID 32508821, 2020). "Recent study has suggested that Smad2/3 phosphorylation is an important event in colitis-associated colorectal cancer and can serve as a biomarker for colitis-associated colorectal cancer." (PMID 26951793, 2016). "Inactivating mutations of Smad2 have been identified in ~6% of colorectal cancers while loss of function mutations of Smad3 are rare in colorectal cancers." (PMID 22204556, 2011). "Mutation analyses of the SMAD-2 gene were carried out on cDNA samples from 36 primary colorectal cancer specimens using a combination of the polymerase chain reaction (PCR), single-strand conformation polymorphism (SSCP) and DNA sequencing." (PMID 9820171, 1998). "Early colorectal carcinoma was found to be associated with Smad2 and Smad4 inactivating mutations." (PMID 32508821, 2020). "Critical components of transforming growth factor β pathway signaling, along with related proteins SMAD2 and SMAD3; SMAD4 and SMAD2 are located on chromosome 18q, a frequent site of loss of heterozygosity in colorectal cancers; inactivated by homozygous deletion or mutation." (PMID 25713610, 2014). "This work aims to clarify the expression patterns of periostin and Smad2/3 signaling in colorectal cancer and their relationship with clinicopathological features." (PMID 39941916, 2025). "Since inhibition of SMAD2/3 linker phosphorylation is proposed as a novel target for colorectal cancer therapy, we investigated the role and presence of pSMAD2L in NSCLC patients, cell lines as well as in primary cells, including AECII and T cells." (PMID 40319202, 2025). "Hence, we hypothesized that in addition to aneuploidy-based loss of Smad2, Smad4, and Dcc in these five colorectal carcinoma tumors, as all our colorectal carcinoma tumors had two copy loss of the floxed Apc allele, the somatic APC copy loss event may also have affected the three known TSGs." (PMID 41051921, 2025). "The long arm of chromosome 18 spans several confirmed and putative tumor suppressors, including Retinoblastoma-Binding Protein 8 (RBBP8), SMAD family members 2 and 4 (SMAD2/4), and deleted in colorectal cancer (DCC)." (PMID 37954063, 2023). "Mesenchymal stem cells secreted TGF-β induced the differentiation of Treg cells via SMAD2 as so to inhibit colorectal cancer." (PMID 36119068, 2022). "LncSNHG1 promotes colorectal cancer cell proliferation and invasion through the miR-181b-5p/SMAD2 axis." (PMID 35310912, 2022). "Around half of the CRLM1 peak genes were related to either increased or decreased gene expression, including increased expression of colorectal cancer genes SMAD2, MAPK9, and GSK3β, as well as three members of GALNT family." (PMID 35907898, 2022).
colorectal cancer (continued). "We will further analyze the role of FAM198B/SMAD2 in colorectal cancer by incorporating more clinical samples in further studies." (PMID 35587159, 2022). "The adenomatous polyposis coli and MADR2/Smad2 genes are found altered in cases of colorectal cancers." (PMID 34205890, 2021). "MIR22HG exerted its tumor suppressive effects through competitively binding to SMAD2 and blocking the association between SMAD4 and SMAD2 in colorectal cancer cells." (PMID 33511320, 2021). "miRNA-140-5p inhibits the progression of colorectal cancer by targeting vascular endothelial growth factor A and mediates the inhibition of Smad2 and autophagy to inhibit the survival and invasion of colorectal cancer stem cells." (PMID 33628799, 2021). "Recently, an increase in FUT3 regulated by DDX39B catalyzes the aberrant L-fucosylation of TGFβR-I, which enhances the DDX39B-mediated TGFβ/SMAD2 signaling pathway and finally facilitates the invasion and metastasis in the colorectal cancer development." (PMID 34485140, 2021). "In our study, the expressions of DCC, Smad2, Smad4, hMLH1, hMSH2, and hMSH3 proteins had been changed, which regulated the colorectal cancer pathway." (PMID 30792708, 2019). "Mechanistically, MnTE-2-PyP attenuated TGF-β-induced EMT in colorectal cancer cells by inhibiting the Smad2/3 signaling pathway." (PMID 30931081, 2019). "For example, two tumor suppressors frequently inactivated in colorectal cancer, SMAD2 and SMAD4, belong to the same protein family and are located within several megabases of each other." (PMID 30697341, 2019). "Our results indicated that MnTE-2-PyP attenuated TGF-β-induced EMT in colorectal cancer cells by inhibiting the Smad2/3 signaling pathway." (PMID 30931081, 2019). "High AQP5 expression correlated with an increase in phosphorylated SMAD2, promoting EMT in colorectal cancer, whereas AQP5 silencing was associated with a down-regulation of phosphorylated SMAD2, and a repressed EMT response." (PMID 29922644, 2018). "A recent study indicated that GDF15 promoted EMT and metastasis in colorectal cancer through binding to the TGF-β receptor to activate Smad2 and Smad3 pathways." (PMID 28199981, 2017). "GDF15 promoted metastasis through the FAK-RhoA signaling pathway in prostate cancer, whereas this metastatic function was achieved through Smad2/3 signaling in colorectal cancer." (PMID 27903972, 2017). "This is in line with in vitro studies where overexpressed HIF-1α in colorectal cancer cells resulted in enhanced GPx1 expression through TGF-βRI/Smad2/ERK1/2/HIF-1α signalling cascade, suggesting transcriptional regulation of GPx1 by HIF-1α." (PMID 27656047, 2016). "Limited studies have been reported on the involvement of non-coding microRNAs (miRNAs) in Smad2 signaling in colorectal cancer stem cells." (PMID 25980495, 2015). "Both SGPP1 and Smad2 mRNA levels were inversely correlated with the miR-27a levels at these human colorectal cancer cells." (PMID 25166914, 2014). "Collectively, these results suggest that Nodal promotes the self-renewal of human CCSCs and mediate carcinogenesis of human colorectal cancer via an autocrine manner through Smad2/3 pathway." (PMID 24696849, 2014). "Compared to the adjacent normal colon mucosa, both SGPP1 and Smad2 expression were much higher at colorectal adenocarcinomas, negatively correlated with miR-27a levels in colorectal cancers in which miR-27a was frequently reduced." (PMID 25166914, 2014). "SGPP1 and Smad2 at mRNA and protein levels were negatively correlated with miR-27a in human colorectal cancer tissues and cancer cell lines." (PMID 25166914, 2014). "The expression of SGPP1 and Smad2 were then evaluated in human colorectal cancers by immunohistochemical staining." (PMID 25166914, 2014). "Chromosome 18q21.1 harbours the tumour suppressor genes SMAD4, SMAD2 and deleted in colorectal cancer (DCC) genes." (PMID 23110075, 2012).
colorectal cancer (continued). "It is localized at chromosome 18q21 together with SMAD2, in a region frequently deleted in colorectal cancers." (PMID 20459617, 2010). "The SMAD-2 gene, which is located at 18q21, has been identified as a candidate tumour-suppressor gene from work on colorectal cancers." (PMID 9820171, 1998). "It was also reported that miR-93-5p suppressed CRC progression via targeting PDL-1, and long non-coding RNA CTBP1-AS2 could modulate the miR-93-5P/TGF-beta/SMAD2/3 pathway in colorectal cancer." (PMID 36230970, 2022). "Moreover, we found that MIR22HG exerts its biological function by inhibiting the growth and migration of colorectal cancer cells through SMAD2 and TGFβ signaling pathway." (PMID 32127004, 2020). "Consequently, these findings demonstrate a functional role by which MnTE-2-PyP inhibits the TGF-β-induced Smad2/3 signaling pathway in colorectal cancer cells." (PMID 30931081, 2019). "LncRNA NORAD, amplified in 13% of samples in colorectal cancer, was mutually exclusive with SMAD2." (PMID 30216655, 2018). "Similarly, hsa-miR-140-5p inhibited colorectal cancer stem cell survival and invasive potential via suppression of Smad2 (mothers against decapentaplegic homolog 2) and autophagy." (PMID 26314959, 2015). "Alterations of SMAD2 are present in about 6% of colorectal carcinoma cases." (PMID 22943793, 2012). "Mutations in SMAD2 or SMAD4 occur frequently in pancreatic and colorectal carcinomas." (PMID 20573232, 2010). "The SMAD-2 gene may play a role as a candidate tumour-suppressor gene in a small fraction of colorectal cancers." (PMID 9820171, 1998). "LOH at 18q indicates presence of several TSGs including Deleted in Colorectal Carcinoma (DCC), SMAD2, and SMAD4; loss of expression of 18q LOH plays a significant role in CRC pathogenesis." (PMID 33374459, 2020). "Similarly, Smad2 and Smad4 proteins had ability to inhibit the growth of colorectal cancer." (PMID 30792708, 2019). "The mutation frequency in colorectal cancer and whether the mutation of Smad2 leads to stability of SMAD2 protein in the colorectal cancer is not clear and warrants further investigation." (PMID 25166914, 2014). "Therefore, miR-27a could be a useful biomarker for colorectal cancer development and progression, and also could have a therapeutic potential targeting SGPP1, Smad2 and Stat3 for colorectal cancer therapy." (PMID 25166914, 2014). "In human colorectal cancer cell lines, AQP5 induced the activation of phosphorylated-mothers against decapentaplegic homolog 2/3 (p-Smad2/3), which resulted in EMT." (PMID 36768212, 2023). "MnTE-2-PyP inhibited the Smad2/3 signaling pathway and the expression of matrix metalloproteinase 2 (MMP-2) and 9 (MMP-9) in colorectal cancer cells, reducing TGF-β-induced EMT and thus invasion of the colorectal and other cancer cells." (PMID 37049670, 2023). "In colorectal cancer, the tumor suppressor gene NIT1 is realized by activating the SMAD2/3 signaling pathway." (PMID 36969909, 2023). "Previous studies have demonstrated that miR-552 functions as a potential oncogene in a series of cancer types and figure out several downstream targets, such as AJAP1 in liver cancer, Smad2 and DACH1 in colorectal cancer, TIMP2 and WIF1 in osteosarcoma 28-32." (PMID 33867818, 2021). "The biological function of asporin inside cancer cells was largely neglected until it was found that asporin interacts with intracellular Smad2/3 and PSMD2 to facilitate gastric and colorectal cancer progression." (PMID 31608236, 2019). "Specifically, MnTE-2-PyP inhibits colorectal cancer cell molecular and morphological changes in response to TGF-β1 through the Smad2/3 signaling pathway." (PMID 30931081, 2019). "Studies have shown that inhibition of BAMBI expression in colorectal cancer can upregulate TGF-β signaling, leading to elevated levels of p-Smad2 and p-Smad3." (PMID 31186664, 2019).
colorectal cancer (continued). "Experimental evidence revealed that asporin interacts directly with Smad2/3 and facilitates the entry of p-Smad2/3 into the nucleus, which induces EMT and colorectal cancer progression." (PMID 31608236, 2019). "Many of these top common pathways are directly involved in CRC, including Regulation of nuclear SMAD2/3 signaling, β-catenin pathway, WNT pathway, TGF-beta signaling pathway, and Colorectal cancer." (PMID 29670137, 2018). "Taken together, this study has revealed miR-27a as a tumor suppressor and has identified SGPP1 and Smad2 as novel targets of miR-27a, linking to STAT3 for regulating cancer cell proliferation, apoptosis and migration in colorectal cancer." (PMID 25166914, 2014). "Using the approaches of miRNA array, systemic biology, in vitro manipulating expression of miR-27a and in vivo tumor-bearing mouse model, we found that miR-27a acted as a tumor suppressor in colorectal cancer, which was through targeting SGPP1 and Smad2." (PMID 25166914, 2014). "SGPP1 and Smad2 protein levels were also downregulated by miR-27a on both HCT116 and SW480 colorectal cancer cells." (PMID 25166914, 2014). "As SGPP1 and Smad2 were likely the targets of miR-27a, we then determined the expression levels of SGPP1 and Smad2 in human colorectal cancers and cancer cell lines." (PMID 25166914, 2014). "Another study on colorectal cancer showed that the exosome circCOL1A1 derived from cancer cells could also promote angiogenesis by recruiting the EIF4A3 protein and activating the Smad2/3 signaling pathway." (PMID 41584514, 2025). "Dll-1 promotes the Wnt and transforming growth factor β (TGF-β) pathways and CTFG gene expression via binding to Smad2/3 and Tof-4, thereby promoting the development of colorectal cancer independent of Notch signaling pathways." (PMID 31198409, 2019). "Our result showed that the expression of Smad2 (not Smad4) protein was up-regulated after T. gondii infection, which indicated the enhanced ability against colorectal cancer." (PMID 30792708, 2019). "Even though components of the TGFβ signaling pathway are often inactivated during CRC progression, it has been shown that active TGFβ signaling—judged by phosphorylation of the downstream components SMAD2/3 (phospho‐SMAD2/3)—can be found in colorectal carcinomas." (PMID 27221051, 2016). "At the same time, some studies demonstrated that p-Smad2 expression level was not related to the prognosis in patients with renal clear cell carcinoma and colorectal cancer." (PMID 25373709, 2014). "Inactivating mutations in SMAD2 and SMAD4 are frequent especially in pancreatic and colorectal carcinomas, although they do not stand for the most frequent tumor changes." (PMID 22943793, 2012). "Moreover, specific siRNA targeting NRP2 or treatment with pharmacological inhibitors of TGFβ-1 type 1 receptor (TGFβRI) prevented Smad2/3 phosphorylation and the NRP2-mediated EMT of colorectal cancer cells." (PMID 21747928, 2011). "However, the patterns of periostin and Smad2/3 expression and their relationship in colorectal cancer have not yet been reported." (PMID 39941916, 2025). "A recent study reported that circPTEN1 bound the MH2 domain of SMAD4 to impair the physical interaction of the circRNA with SMAD2/3, which inhibited the formation and nuclear translocation of SMAD complexes and subsequently inhibited the transcription of TGF-β induced EMT genes in colorectal cancer." (PMID 37689715, 2023).
colorectal cancer (continued). "Therefore, miR-27a could be a useful biomarker for monitoring colorectal cancer development and progression, and also could have a therapeutic potential by targeting SGPP1, Smad2 and STAT3 for colorectal cancer therapy." (PMID 25166914, 2014).